GSDME (gasdermin E)
Diseases named in the same sentence as GSDME in open-access papers (continued):
Sharing a sentence is not in itself a finding about the gene and the disease.
tumor (continued). "Pyroptosis marker, including GSDME‐N, was also detected in the HMB and combination treatment groups, indicating that HMB‐induced GSDME‐dependent pyroptosis enhanced tumor immunogenicity." (PMID 39950759, 2025). "This pH- and ultrasound-responsive platform enables tumor microenvironment-specific drug release, achieving precise induction of pyroptosis through localized upregulation of GSDME expression and caspase-3 activation." (PMID 40721578, 2025). "Concurrently, to determine if 2-DG induces pyroptosis in vivo, expression of caspase-3, GSDME, IL-18, and IL-1β was analysed in tumor tissues." (PMID 41415273, 2025). "Ki67 staining resultssuggested that the Lenvatinib treatment was most effective in the GSDME overexpression group, significantly inhibiting the proliferation of tumor." (PMID 40653759, 2025). "In vitro, CCCR-NK92 cells rapidly kill tumor cells by inducing GSDME-mediated pyroptosis and significantly inhibit tumor growth in a cancer xenograft model." (PMID 39917567, 2025). "CAR T cell-induced pyroptosis further illustrates this complexity: granzyme B activates caspase-3 and GSDME in tumor cells, which triggers caspase-1-dependent GSDMD in macrophages, causing cytokine release syndrome." (PMID 41291696, 2025). "Our study demonstrated that EVLPs inhibited tumor growth through caspases-3/9 activation and GSDME cleavage in Panc-1 cell and its xenograft models." (PMID 40604924, 2025). "The epigenetic inactivation of GSDME, which functions as a crucial tumor suppressor gene, is commonly observed in various types of cancers." (PMID 40568597, 2025). "Mechanistically, DHODH inhibition by H62 disrupted mitochondrial homeostasis, leading to increased ROS, caspase-3 activation, and cleavage of GSDME, which together initiated pyroptotic tumor cell death." (PMID 41239499, 2025). "The treatment induced GSDME upregulation would further synergize with radiation induced caspase activation to promote pyroptosis of tumor cells." (PMID 41041050, 2025). "Once cleaved and activated by caspase-3, GSDME can convert apoptosis programs in tumor cells into secondary inflammatory cell death in the form of pyroptosis." (PMID 40345706, 2025). "One is to motivate the pore-forming activity of GSDME to trigger tumor cell pyroptosis; another is to activate anti-tumor immune response." (PMID 39816682, 2025). "One study demonstrated that CAR‐T cells mediate the GZMB/GSDME/CASP3 signalling axis to accomplish the pyroptosis of tumour cells." (PMID 38652105, 2024). "In future research, researchers need to comprehensively analyse the activation mechanism and functional principles of GSDME in cells and explore the profound impact of cell pyroptosis that is mediated by GSDME on the tumor microenvironment." (PMID 39526199, 2024). "On the one hand, HLA-treated tumor cells displayed the cleavage of Caspase-3 and Gasdermin E (GSDME), a pyroptosis-like cellular morphology, and cell lysis, but on the other hand, HLA-treated splenic T cells showed selective expansion of CD8+ T cells." (PMID 38191648, 2024). "The second way in which GSDME exerts its anticancer effects is through a positive correlation between its expression and the phagocytosis of tumor-related macrophages, as well as the production and function of NK and CD8+ T lymphocytes." (PMID 38169676, 2024). "The PLK1 inhibitor, BI2536 and the alkylating agent, cisplatin, promoted the development of tubular squamous cell carcinoma (ESCC) into pyroptosis and inhibited tumour progression by augmenting the caspase‐3/GSDME pathway." (PMID 38652105, 2024). "Increased expression of GSDME in cancer cells not only boosts NK cell numbers but also enhances their ability to kill tumor cells." (PMID 38987821, 2024). "Suppression of CDC20 expression results in elevated levels of GSDME, thereby promoting pyroptosis and enhancing anti-tumor immune responses." (PMID 39223632, 2024).
tumor (continued). "Regarding the regulatory relationship between ferroptosis and pyroptosis, Professor Wu Qiao's group reported that Fe2 + and drugs that induce ROS elevation can induce pyroptosis via a Tom20-Bax-caspase-GSDME pathway, thus controlling tumour development." (PMID 38499622, 2024). "Arsenic trioxide (As2O3) is known to initiate pyroptosis in HCC by activating caspase-3-mediated cleavage of GSDME, subsequently halting tumor progression." (PMID 39117626, 2024). "Neobractatin (NBT), isolated from the edible fruit of Garcinia bracteata, can induce GSDME cleavage by activating caspase-3 in esophageal cancer (EC) cells, resulting in cell death and tumor growth inhibition." (PMID 39062587, 2024). "After IFN treatment, the loss of USP18 not only induces pyroptosis through GSDMD but also, with the involvement of PLK2, triggers pyroptosis through GSDME, leading to suppressed tumor growth in USP18-depleted conditions." (PMID 39223632, 2024). "In CAR-T Cell Therapy, CAR-T cells induce pyroptosis in tumor cells by activating the caspase-3/GSDME pathway through GzmB release." (PMID 38987821, 2024). "The main mechanism of action is that (BRAFi + MEKi) promotes the cleavage of GSDME while inducing pyroptosis and release of DAMPs to activate the activity of immune cells in the TME to cause anti‐tumour immunity." (PMID 38652105, 2024). "Recently, it has been found that GzmB can directly cleave GSDME in tumor cells, thereby inducing pyroptosis and further activating anti-tumor immune responses." (PMID 38380334, 2024). "Recent studies have shown that GZMB cleaves GSDME-mediated pyroptosis in target cells, leading to enhanced anti-tumor immunity and reduced tumor growth." (PMID 38773976, 2024). "Multiple research studies have suggested that GSDME has the potential to serve as an important target for tumor chemotherapy." (PMID 38902235, 2024). "On the other hand, caspase-8 has also been shown to act as a downstream of granzymes, specifically inducing GSDME cleavage and inducing pyroptosis, thus further activating anti-tumor immune response and inhibiting tumor growth." (PMID 38553639, 2024). "The mechanism shows that GSDME in tumor cells is able to recruit killer lymphocytes and activate caspase-independent pyroptosis by directly cleaving GSDME." (PMID 39329964, 2024). "In the caspase-3/GSDME signaling pathway, cytotoxic drugs-induced tumor cell death via caspase-3-dependent pyroptosis or apoptosis under the expression of high or low levels of GSDME." (PMID 38553639, 2024). "Previous studies showed that GSDME is activated by apoptotic caspase-3, driving tumor cell pyroptosis and anti-tumor immunity." (PMID 38195694, 2024). "GSDME, as a key member of the apoptosis and pyroptosis crosstalk events, has also been shown to have anti-tumor effects." (PMID 38553639, 2024). "Their study found that tumor cells with high GSDME expression exhibited typical pyroptosis morphology after receiving RT, including cell swelling and pore formation on plasma membranes." (PMID 39398428, 2024). "In tumours with high GSDME expression, GSDME can induce a switch from caspase-3-mediated apoptosis induced by chemotherapeutic agents to pyroptosis." (PMID 38906860, 2024). "The expression levels of GSDME determine the fate of tumor cells in response to the caspase 3 activators." (PMID 38388468, 2024). "During in vivo studies, PEG‐CuP‐COF@∆St nanosystem with its self‐driven property exhibited impressive tumor‐targeting capability and activated Caspase‐3/gasdermin E‐dependent pyroptosis to inhibit tumor growth." (PMID 39494618, 2024). "Certain pharmaceutical agents can stimulate tumor cells to undergo pyroptosis via the caspase-3/GSDME pathway." (PMID 39796003, 2024). "In many tumor cells, the expression of GSDME is significantly reduced due to the methylation of the promoter region of the DFNA5 gene, which encodes GSDME, thereby decreasing the efficiency of pyroptosis induction." (PMID 39221221, 2024).
tumor (continued). "The CRISPR/dCas9 component activates the tumor's own GSDME gene, while cisplatin induces caspase-3 activation, which cleaves the newly synthesized GSDME, triggering potent pyroptosis." (PMID 39221221, 2024). "For instance, dioscin, a natural compound, has been shown to kill osteosarcoma cells and inhibit tumor growth through the caspase-3/GSDME axis-mediated pyroptosis." (PMID 39201755, 2024). "Studies have identified that multiple chemotherapy agents can trigger caspase-3-mediated pyroptosis in tumor cells with elevated levels of GSDME, thereby boosting the immunogenicity of these cells." (PMID 39221221, 2024). "Not only that, but GSDME expression also enhanced phagocytosis by TAMs as well as infiltration of NK cells, implying that the anti-tumor effects of GSDME are closely related to NK and CD8+ T." (PMID 38553639, 2024). "The oncolytic Parapoxvirus ovis (ORFV) reduces the ubiquitination of GSDME, stabilizing it and initiating cell pyroptosis, thereby enhancing tumor sensitivity to immune checkpoint inhibitors." (PMID 39223632, 2024). "It was shown that high expression of GSDME, which causes pyroptosis, enhances the number and function of CD8 T cells in tumor cells." (PMID 38178669, 2024). "Our results revealed that GSDME expression was significantly lower in tumor tissues compared to adjacent normal tissues." (PMID 38902235, 2024). "It has also been shown that the platinum‐based third‐generation agent Lobaplatin eradicates tumour cells through GSDME‐dependent pyroptosis." (PMID 38214430, 2024). "First, in the context of chimeric antigen receptor T-cell (CAR-T) immunotherapy, granzyme B released by CAR-T cells was shown to activate the caspase-3/GSDME axis in tumor cells, inducing pyroptosis." (PMID 39201755, 2024). "In tumors exhibiting immune cell infiltration, a high expression of GSDMD and GSDME often accompanies this phenomenon, indicating tumor pyroptosis and the immune response exhibit a mutually reinforcing positive feedback mechanism." (PMID 39069522, 2024). "Recent studies have shown that chemotherapy drugs induce pyroptosis in tumor cells mediated by gasdermin E (GSDME), a key protein within the gasdermin family that is cleaved by activated caspase-3." (PMID 38177154, 2024). "GSDMA, GSDMB, GSDMD, and GSDME displayed significantly higher expression in tumor stage 2 and 3 than in normal tissues." (PMID 39607202, 2024). "To summarize, the GSDME expression in tumor cells is a predictor of radiosensitivity and conferred radiotherapy prognosis in various tumors." (PMID 38323315, 2024). "Gasdermin-E (GSDME), the executioner of pyroptosis when cleaved by caspase 3, plays a crucial role in tumor defense and the response to chemotherapy drugs in cells." (PMID 38238307, 2024). "For instance, harnessing microRNA to reactivate GSDME expression, in combination with cetuximab, has demonstrated promising results in initiating pyroptosis in malignant cells and reducing tumor size in mouse models of aggressive triple-negative breast cancer." (PMID 38304430, 2024). "Pyroptosis belongs to a unique type of programmed cell death among which GSDME is reported to exert anti-tumor immunity." (PMID 38853246, 2024). "When GSDME mediates pyroptosis, it can increase the sensitivity of cancer cells to antitumor drugs, thereby promoting the death of tumor cells." (PMID 39526199, 2024). "Among these, COF-909-Cu was particularly effective, significantly inducing GSDME-dependent pyroptosis and bolstering anti-tumor immunity in vivo." (PMID 39221221, 2024). "Increased expression of GSDME enhances the phagocytic activity against tumor cells, thereby inhibiting tumor growth." (PMID 39062587, 2024). "Recently, GSDME-mediated pyroptosis is reported to stimulate antitumour immunity and inhibit tumour growth." (PMID 38906860, 2024). "BRAFi + MEKi treatment led to GSDME-dependent tumor clearance and the establishment of antitumor immunity." (PMID 38391959, 2024).
tumor (continued). "Individually, these elements are insufficient for effective tumor control; however, the concurrent action of cisplatin and the autogenous supply of GSDME leads to a significant reduction in tumor growth in both primary and recurrent melanoma models." (PMID 39501932, 2024). "Conversely, GSDME-KO SCLC subcutaneous tumors were substantially larger than those in the NC group, and the simultaneous administration of IL-12 caused tumor shrinkage." (PMID 38169676, 2024). "The activated caspase-3 cleaves GSDME to form the pore-forming active GSDME-N, which perforates the tumor cell membrane, ultimately leading to tumor cell pyroptosis." (PMID 40630838, 2024). "MPNPs + oHSV treatment resulted in CASP3/GSDME-mediated tumor cell pyroptosis, which inhibited tumor growth in a 4T1 TNBC model." (PMID 38391959, 2024). "GSDME acts like a switch molecule for the transformation between apoptosis and pyroptosis, such that overexpressed GSDME triggers tumour cell death through caspase-3-dependent pyroptosis, whereas its low levels transit cell death mode to apoptosis." (PMID 38172670, 2024). "Mechanistically, while tumor cells treated with HLA display Gasdermin E (GSDME) cleavage and a cellular phenotype resembling pyroptosis, splenic T cells incubated with HLA lead to selective expansion of CD8+ T cells." (PMID 38191648, 2024). "Previous researchers have documented that chemotherapy has the potential to shift cell death from apoptosis to pyroptosis through caspase-3-mediated GSDME cleavage, particularly in tumor cells exhibiting elevated GSDME expression." (PMID 38756442, 2024). "This GA induced GSDME-dependent pyroptosis and significantly suppressed tumor proliferation, while enhancing anti-tumor activity." (PMID 39062587, 2024). "The MPNPs can induce tumor cell pyroptosis on their own via the CASP3/GSDME axis, but maximum efficacy was achieved when combined with oncolytic herpes simplex virus 1 (oHSV)." (PMID 38391959, 2024). "Using UPS‐assisted genome editing, the expression of gasdermin E was effectively restored in 4T1 tumor‐bearing mice, achieving pyroptosis‐mediated antitumor immunotherapy through low‐dose X‐ray irradiation." (PMID 39501932, 2024). "This implies that microwave treatment can be used to generate a significant quantity of ROS in tumor cells to activate caspase-3, thereby triggering GSDME protein-based pyroptosis." (PMID 40630838, 2024). "In 2020, it was reported that cleaved GSDME activated pyroptosis, further activating the antitumor immune response and inhibiting tumor growth." (PMID 39559553, 2024). "In recent years, more and more studies have shown that GSDME-mediated pyroptosis has a good anti-tumor effect." (PMID 37658132, 2023). "GSDME-mediated pyroptosis has also been shown to exert a tumor suppressive role by increasing numbers of NKs and T cells while decreasing M2 macrophages and MDSCs." (PMID 37373523, 2023). "According to previous reports, GSDME is generally expressed at low levels in tumor cells because of the hypermethylation of its promoter." (PMID 35651286, 2023). "In antitumour therapy, GSDME protein levels are crucial for caspase-3/GSDME-mediated tumour cell pyroptosis." (PMID 37781519, 2023). "Treatment with the methylation inhibitor 5‐aza‐dC promotes GSDME expression and inhibits tumor cell proliferation and tumorigenesis, suggesting GSDME as a novel tumor suppressor gene in CRC." (PMID 37125240, 2023). "GSDME-mediated pyroptosis leads to an augmented infiltration of natural killer (NK) cells and CD8+ T lymphocytes and induces phagocytosis by tumor-associated macrophages, further contributing to the anti-tumor response." (PMID 38144182, 2023). "Ectopic expression of mouse GSDME in BALB/c mouse 4T1E breast cancer cells significantly inhibited 4T1E tumor growth and led to increased tumor-associated macrophage and natural killer (NK cell) infiltration." (PMID 38020781, 2023).
tumor (continued). "DCT is a DNA methylation inhibitor used to activate the gasdermin E (GSDME) gene, which is frequently methylated and silenced in most tumor cells." (PMID 37895165, 2023). "Consistently, GSDME protein enhancement and cleavage has been simultaneously observed in the tumors from tumor-bearing mice after intratumoral treatment of ORFV (105 TCID50)." (PMID 36641456, 2023). "Consistently, GSDME depletion reduces the proportion of intratumoral cytotoxic T lymphocytes, pyroptotic cell death and the success of tumor ORFV virotherapy." (PMID 36641456, 2023). "DAC is a DNA methyltransferase (DNMT) inhibitor, which can inhibit the methylation of GSDME in tumor cells." (PMID 36605484, 2023). "Treating melanoma patients with BRAF/MEK inhibitors induces GSDME-dependent pyroptosis and supports anti-tumor immune responses." (PMID 37771587, 2023). "Previous research studies show that GSDMD is required for CD8+ T cell cytotoxicity toward LC cells, and GSDME represses tumor growth in vivo." (PMID 36941988, 2023). "For instance, Oncolytic parapoxvirus (ORFV) stabilizes GSDME by reducing its ubiquitination, leading to tumor cell pyroptosis." (PMID 37965452, 2023). "GSDME expression increases the phagocytic capacity of TAMs and the cytotoxic T cell population and enhances anti-tumor immunity." (PMID 37542283, 2023). "Although both GSDMB and GSDME can be activated by killer cells, it seems that GSDME is a more potent tumor suppressor than GSDMB, probably due to the initiation and amplification of GSDME pyroptosis by Caspase-3 in tumors." (PMID 36742298, 2023). "During tumor formation, GSDME is in a state of transcriptional repression through methylation modification." (PMID 37658132, 2023). "Given that wild-type (WT) ORFV can trigger GSDME-mediated tumor cell pyroptosis, we further generated ORFV recombinants by deleting a different set of virulence genes, and examine the ability of ORFV recombinants on inducing pro-inflammatory cell pyroptosis." (PMID 36641456, 2023). "Another investigation demonstrated that oncolytic parapoxvirus ovis (ORFV), a promising biotherapeutic antitumour agent, promotes tumour cell pyroptosis by decreasing GSDME ubiquitination." (PMID 37781519, 2023). "Accompanied by the decrease of tumor-infiltrating lymphocytes, GSDME depletion also contributed to accelerate the tumor growth under the treatment of ORFV, which was confirmed by the changes of endpoint tumor weight." (PMID 36641456, 2023). "We observed that PD-1 blockade was able to markedly extend the survival of ORFV pretreated mice, which further supported that oncolytic ORFV can harness GSDME, recruit CTLs and further remodel tumor immune microenvironment." (PMID 36641456, 2023). "Above all, depletion of CDC20 enhances the anti-tumor immunity and synergistic effects with α-PD-1 mediated by GSDME." (PMID 37528490, 2023). "Oncolytic parapoxvirus ovis (ORFV) promoted intratumoral infiltration of CTLs and exhibited tumor killing effects in vivo by inducing GSDME-dependent pyroptosis in cancer cells." (PMID 38283351, 2023). "Although GSDME is expressed in only a small number of tumor cells, a small number of tumor cells undergoing pyroptosis are sufficient to modulate the tumor immune microenvironment and activate a powerful T-cell-mediated antitumor immune response." (PMID 36605484, 2023). "Many studies have shown that DNA methylation reduces the expression of GSDME in most tumor cells, making it difficult to induce pyroptosis in tumor cells." (PMID 36867605, 2023). "Caspase-3 can induce a pyroptosis-like process in tumor cells that are otherwise in the process of apoptosis via gasdermin-E (GSDME), a homologous protein of GSDMD." (PMID 36744134, 2023). "In mouse tumor models, knockdown of GSDME enhanced tumor growth, whereas ectopic expression of GSDME inhibited tumor growth." (PMID 36920176, 2023).